IFNG (interferon gamma)
Diseases named in the same sentence as IFNG in open-access papers (continued):
Sharing a sentence is not in itself a finding about the gene and the disease.
brain cancer (6 papers, 2017 to 2022). A primary or metastatic malignant neoplasm affecting the brain. "HDAC4 protein stimulates IFNγ (Type 2 interferon signaling) and HDAC inhibition is considered a potential therapeutic strategy in pediatric brain cancers." (PMID 36293188, 2022).
breast invasive carcinoma (6 papers, 2017 to 2025). "In this study, we assessed the correlation between the pretreatment peripheral blood NK cell activity measured by released interferon-gamma and the clinicopathological characteristics of patients diagnosed with curable invasive breast cancer." (PMID 38674146, 2024). "However, a previous study revealed that different immunoreaction to IFNγ in three breast lesions (benign, in situ and infiltrating breast cancers) with the highest level in the in situ lesion." (PMID 29156701, 2017). "Our finding also exhibited a positive correlation between IL‐18 and YAP1 via IFNG gene expression and showed that IL‐18 expression is positively correlated with YAP1 in breast invasive carcinoma." (PMID 34196131, 2022). "In addition, the overall oncoprint of YAP1, IL‐18 and IFNG gene expressions in Breast Invasive Carcinoma (PanCancer Atlas) cohort showed that mRNA expression was up‐regulated by 3.02, 2.82, and 3.22% (YAP1, IL18 and IFNG) in all patients, respectively." (PMID 34196131, 2022). "In conclusion, the present data analysis suggests that IL‐18 might influence YAP1 in Breast oncogenesis through the production of IFNG and IL‐18 expression is positively correlated with YAP1 expression in breast invasive carcinoma." (PMID 34196131, 2022).
cerebral infarction (6 papers, 2013 to 2025). An ischemic condition of the brain, producing a persistent focal neurological deficit in the area of distribution of the cerebral arteries. "The higher levels of proinflammatory tumor necrosis factor (TNF-α), interleukin-6 (IL-6), and interferon-gamma (IFN-γ) in the plasma of focal cerebral ischemia monkeys suggest both intestinal microecological dysregulation and chronic systemic inflammation following cerebral infarction." (PMID 36267243, 2022).
cholestasis (6 papers, 2017 to 2025). Impairment of the bile flow caused by obstruction within the liver, or outside the liver in the bile duct system. "In contrast, IFNγ had a protective effect on the CCl4 model and cholestasis model by bile duct ligation." (PMID 38907339, 2024).
Ebola (6 papers, 2015 to 2025). "This has been supported in mouse models of infection with Ebola, West Nile, and murine corona viruses, where IFNγ was critical in controlling these pathogens." (PMID 37298195, 2023). "In addition, one study which compared survivors with PES to survivors without sequelae found had an increased CD8+ T-cell and CD4+ T-cell expression of IFNγ and TNFα following stimulation with Ebola antigens." (PMID 40561148, 2025).
Epstein-Barr virus infection (6 papers, 2014 to 2025). An infection that is caused by Epstein-Barr virus. "Cluster 2 contains interferon gamma signaling, the herpes simplex infection pathway, and the Epstein-Barr virus infection pathway." (PMID 31739287, 2019).
giant cell arteritis (6 papers, 2016 to 2022). "One key pathological finding in giant cell arteritis (GCA) is the presence of interferon-gamma and interleukin (IL)-17 producing T helper (Th) 1 and Th17 cells in affected arteries." (PMID 34404463, 2021).
herpes simplex infection (6 papers, 2019 to 2024). "Meanwhile, enriched pathways stimulated by up-regulated DEGs mainly included the regulation of defense response, response to interferon-beta, response to virus, response to interferon-gamma, inflammatory response, Herpes simplex infection." (PMID 33923285, 2021). "Besides, all DEGs activated a series of pathways, including regulation of defense response, response to interferon-beta, response to virus, response to interferon-gamma, inflammatory response, and Herpes simplex infection." (PMID 33923285, 2021). "The brown module, containing 2870 mRNAs and 769 non-coding RNAs, is among others highly enriched in the GO_BP terms viral process, response to interferon-gamma and innate immune response, as well as the pathways interferon signaling, herpes simplex infection and adaptive immune system." (PMID 33086748, 2020).
Huntington disease (6 papers, 2018 to 2023). Huntington disease (HD) is a rare neurodegenerative disorder of the central nervous system characterized by unwanted choreatic movements, behavioral and psychiatric disturbances and dementia. "Cluster 4 was enriched for pathways involved in apoptosis, response to interferon-gamma (IFN-γ) and mitochondrial and respiratory functions, including Alzheimer, Parkinson and Huntington disease KEGG pathways." (PMID 37248328, 2023). "Interestingly, at 14 weeks of age, we found a decrease in IFNγ levels in female Huntington’s disease mice (P = 0.02) and, at 20 weeks of age, we saw a trend for male Huntington’s disease mice to have decreased IFNγ levels (P = 0.059)." (PMID 36035436, 2022). "Finally, Bax, Hdac2 and Sp1, involved in apoptosis and transcription, are found among the Huntington’s disease-specific genes affected by LPS and LPS + IFNγ." (PMID 30382133, 2018).
Hyperinsulinemia (6 papers, 2013 to 2025). An increased concentration of insulin in the blood. "Insulin suppressed IFNγ production and induced the senescence-associated secretome in CD4+ cell cultures and in patients with hyperinsulinemia." (PMID 39768214, 2024). "Together, this transcriptional profile supported our experimental findings and provided a molecular basis for the arrest of IFNγ production, and suggested the reduced frequency of Th1 cells in patients with hyperinsulinemia." (PMID 39768214, 2024). "In both cultured CD4+ cells and those isolated from patients with hyperinsulinemia, insulin inhibited IFNγ production by repressing key Th1 transcription factors and cell surface receptors essential for IFNγ signaling." (PMID 39768214, 2024). "Indeed, the IFNG gene was the top gene repressed in CD4+ cells of patients with hyperinsulinemia." (PMID 39768214, 2024). "Our study showed a link between hyperinsulinemia and IFN pathway genes, emphasizing the biological context in shaping IFNγ effects." (PMID 39768214, 2024). "Since acute stimulation with insulin inhibited IFNγ production in CD4+ cells, we asked if chronic hyperinsulinemia mirrored this effect." (PMID 39768214, 2024). "In a recent manuscript, it was reported that IL-1β produced by macrophages inside Langerhans islets in response to strong infection was not sufficient to induce hyperinsulinemia; a systemic surge of IFNγ was also required." (PMID 39107476, 2024). "Notably, infection with a high viral dose lowered blood glucose levels, which was dependent on cytokines such as IL-1β, IL-1α, IFNγ and TNF and proposed to be the result of hyperinsulinemia." (PMID 39107476, 2024).
inclusion body myositis (6 papers, 2020 to 2025). A slowly progressive degenerative inflammatory disorder of skeletal muscles characterized by late onset weakness of specific muscles and distinctive histopathological features. "The virally induced senescent, interferon gamma-producing cytotoxic CD8+ T cells with increased inflammatory, and cytotoxic features are involved in the occurrence of inclusion body myositis in most such cases, in a genetically predisposed host." (PMID 38693436, 2024). "Skeletal muscle of patients with sporadic inclusion body myositis (sIBM) presents with inflammation, including upregulation of inflammatory cytokines such as interferon γ (IFNγ)." (PMID 37731843, 2023). "In contrast, HLA class II genes typically induced by T cell-derived IFNγ were more strongly upregulated in ANCA-negative VM than in DM, comparable to those in antisynthetase syndrome (AS) and lower than in inclusion body myositis (IBM)." (PMID 41441888, 2025).
microcephaly (6 papers, 2020 to 2025). A congenital or acquired developmental disorder in which the circumference of the head is smaller than normal for the person's age and sex. "Gene expression quantified by qPCR in whole blood samples showed an increase in IFNγ and IL-13 transcripts in children affected with microcephaly compared to the control group." (PMID 37766239, 2023). "In this study, we demonstrate that children with microcephaly due to CZS present dysregulation of antagonistic inflammatory mediators, characterized by increased mRNA expression of IFNγ and IL-13." (PMID 37766239, 2023).
myeloid malignancies (6 papers, 2015 to 2025). "We have shown that our expanded NK cells, currently used in several clinical trials for myeloid malignancies and posterior fossa tumors (NCT01787474, NCT01904136, NCT01823198, NCT02271711), secrete large amounts of IFNγ compared to primary NK cells." (PMID 28428785, 2017). "Taken together, in two different preclinical models of myeloid malignancies (APL and HR-MDS) the survival advantage induced by the pVAX14 vaccine was concomitant with increases in IFNγ producing cells, memT, leukemic precursor-specific CD3+ cells and MyD88 expression." (PMID 26378812, 2015).
myeloproliferative neoplasm (6 papers, 2013 to 2025). A clonal hematopoietic stem cell disorder, characterized by proliferation in the bone marrow of one or more of the myeloid (i.e., granulocytic, erythroid, megakaryocytic, and mast cell) lineages. "Key to Rux efficacy is its broad anti-inflammatory activity against the myeloproliferative neoplasm (MPN) inherent cytokine storm with pro-inflammatory IL-1, IL-6, IL-8, IL-12, TNF-α, IFNγ, VEGF, TGFβ, FGF, PDGF, GM-CSF, and G-CSF cytokines/growth factors." (PMID 32518419, 2020). "Activation of the JAK2/STAT1 pathway, not necessarily through phosphorylated STAT1, is related to myeloproliferative neoplasms, and blockade of IFNγ reduced melanomagenesis." (PMID 24065129, 2013).
necrotizing enterocolitis (6 papers, 2017 to 2023). Necrotizing enterocolitis (NEC) is a devastating disease that affects mostly the intestine of premature infants. "TNFα and IFNγ are key cytokines mediating innate and adaptive immune cell activity in the gut during bacterial infection and in necrotizing enterocolitis." (PMID 29110754, 2017).
nephrotic syndrome (6 papers, 2020 to 2024). A collection of symptoms that include severe edema, proteinuria, and hypoalbuminemia; it is indicative of renal dysfunction. "Compared to the control group, for the nephrotic syndrome group, total salivary protein was significantly lower, as were the levels of all the cytokines examined except IFNγ." (PMID 32825238, 2020).
Newcastle disease (6 papers, 2012 to 2025). A condition caused by infection by the Newcastle disease virus, which may be characterized by conjunctivitis, respiratory illness, and diarrhea. "Given its immunomodulatory characteristics, Cs has been used as an adjuvant in vaccines against Newcastle disease, parvovirus, and salmonella, promoting IFNγ production and the proliferation of CD4 as well as CD8 T lymphocytes." (PMID 40733140, 2025).
polyarticular JIA (6 papers, 2018 to 2021). "Higher levels of interferon gamma (IFNγ) are found in synovial fluid from patients with ERA compared to those with polyarticular JIA." (PMID 34136509, 2021). "IFNγ has been associated with innate and adaptive responses in adult RA, with some reported association with systemic-onset JIA but not with oligoarticular or RF− polyarticular JIA." (PMID 30127787, 2018).
primary biliary cholangitis (6 papers, 2012 to 2023). Primary biliary cholangitis (PBC) is a chronic and slowly progressive cholestatic liver disease of autoimmune etiology characterized by injury of the intrahepatic bile ducts that may eventually lead to liver failure. "Here, we compared hepatic gene expression profiles among high-fat diet (HFD) mice using the primary biliary cholangitis (PBC) mouse model based on the chronic expression of interferon gamma (IFNγ) (ARE-Del-/- mice)." (PMID 33379198, 2020).
Primary hemophagocytic lymphohistiocytosis (6 papers, 2020 to 2024). "Primary hemophagocytic lymphohistiocytosis (pHLH) is an inherited inflammatory syndrome driven by the exuberant activation of interferon-gamma (IFNg)-producing CD8 T cells." (PMID 37228616, 2023).
retinitis (6 papers, 2015 to 2025). Inflammation of the retina. "The relative expression of IFNγ and IFNα (Both inducers of CXCL 9 and CXCL10) were elevated in case of patients with retinitis." (PMID 35538132, 2022).
secondary progressive MS (6 papers, 2015 to 2023). "In secondary progressive MS (SPMS) post-mortem brains, greater leptomeningeal inflammation and grey matter demyelination were associated with elevated CSF protein levels of the proinflammatory cytokines TNF and IFNγ and the B-lymphocyte chemokine CXCL13." (PMID 32398070, 2020).
sensitization (6 papers, 2012 to 2023). "Herpes-associated EM (HAEM) is a hypersensitivity reaction in which CD4+Th1 cells produce IFN-γ (interferon-gamma)." (PMID 37908411, 2023).
synovial sarcoma (6 papers, 2017 to 2022). "The phase 2 clinical trial NCT03063632 for example, investigating the combination of IFNγ and pembrolizumab, included patients with synovial sarcoma as one of its cohorts." (PMID 36686827, 2022). "This phase 0 trial indicated that IFNγ can convert a “cold” into a “hot” tumour in patients with synovial sarcoma and myxoid/round cell liposarcoma, and the combination with anti-PD1 treatment may produce some advantages in the treatment of this patients." (PMID 36686827, 2022). "However, we also found non-zero interferon gamma (IFNG) expression in half of the synovial sarcoma samples that we analyzed, therefore we hypothesize that there are functional and active T cells in those tumors that may be exploited to develop effective immunotherapies." (PMID 28630682, 2017).
temporal lobe epilepsy (6 papers, 2016 to 2026). A localization-related (focal) form of epilepsy characterized by recurrent seizures that arise from foci within the temporal lobe, most commonly from its mesial aspect. "Additionally, patients with temporal lobe epilepsy have also been reported to have increased levels of interferon gamma." (PMID 28008305, 2016).
trypanosomiasis (6 papers, 2009 to 2025). Infection with protozoa of the genus trypanosoma. "This is also the case in trypanosomiasis, as production of the cytokine IFNγ from T cells and natural killer (NK) cells is required to drive effector responses such as the development of T helper 1 cells and macrophage activation." (PMID 41191641, 2025).
vitamin A deficiency (6 papers, 2012 to 2023). Deficiency of vitamin A due to malnutrition, malabsorption, or dietary lack. "The higher mean concentrations of IFNγ associated with vitamin A deficiency found in this study are in line with what has been previously reported elsewhere." (PMID 37111135, 2023). "The concentration of IFNγ was associated with Plasmodium falciparum and Entamoeba histolytica/Entamoeba dispar/Entamoeba moshkovskii infections, vitamin A deficiency, attending the most remote schools and low socioeconomic status." (PMID 37111135, 2023). "In contrast to S. mansoni infection, we found that the numbers of GP61 and GP33 peptide-specific IFNγ- or TNFα-positive CD4+ or CD8+ T cells in the livers, spleens and MLN of LCMV-infected mice were unaffected by vitamin A deficiency." (PMID 22927819, 2012). "By quantitative real-time PCR analysis (qRT-PCR) of isolated liver lymphocytes, we found that vitamin A deficiency significantly reduced the expression of IL-4, IL-5, and IL-13 but not of IFNγ." (PMID 22927819, 2012). "Vitamin A deficiency results in debilitated cellular immune responses, such as a decrease in CD4+ and CD8+ intraepithelial lymphocytes (IEL), mitogen-induced splenic lymphocyte proliferation, and reduced serum interferon-gamma (IFN-γ) production during Eimeria acervulina infection." (PMID 33705619, 2021). "Concomitantly, the numbers of IFNγ+ and TNFα+ CD4+ T cells were not decreased in A− mice, indicating a selective defect in the TH2 response induced by vitamin A deficiency." (PMID 22927819, 2012).
anaplasmosis (5 papers, 2013 to 2025). "For example, Anaplasma phagocytophilum infection leads to disruption of the IFN-γ (interferon-gamma) signaling pathways and downstream phagocytosis events by neutrophils." (PMID 36817439, 2023).
colorectal adenocarcinoma (5 papers, 2017 to 2023). The most common type of colorectal carcinoma. "Here, we found that sustained innate IL-25 and ILC2 signals helped to maintain a cancer-permissive microenvironment in intestinal polyps and colorectal adenocarcinoma, by preventing anti-tumoral T cell and IFNγ-mediated immunity." (PMID 35658010, 2022). "In trefoil factor 3 (TFF3) overexpressing colorectal adenocarcinoma cells (HT-29/B6), we observed enhanced resistance against TNF-α/interferon gamma-induced apoptosis." (PMID 28149533, 2017).
complication (5 papers, 2012 to 2024). Any disease or disorder that occurs during the course of, or because of, another disease, treatment, or procedure. "Moreover, the presence of pulmonary complications was closely associated with an increase in the circulation of the proportion of short-living effector CD27–CD62L–CD8+ T cells, as well as mature T cells capable of producing perforin, granzyme B, and IFNγ." (PMID 34832564, 2021).
Down syndrome (5 papers, 2010 to 2025). "The levels of IFNγ, TNFα, IL-10 in the Down syndrome group (DS) were higher than in the intellectual Disabilities (ID) group (p < 0.05)." (PMID 21496308, 2011). "The median value of IFNγ was 389.2 pg/ml in the Down syndrome group (DS) and 43.55 pg/ml in the Intellectual disabilities group (ID) with p = 0.011." (PMID 21496308, 2011).
Encephalopathy (5 papers, 2021 to 2025). Encephalopathy is a term that means brain disease, damage, or malfunction. "Key laboratory findings included significantly lower levels of interferon-gamma (IFN-γ) (P < .001), tumor necrosis factor-alpha (TNF-α) (P < .001), and a decreased CD4+/CD8 + ratio (P = .001) compared to the non-encephalopathy group." (PMID 41189156, 2025).
fetal growth restriction (5 papers, 2021 to 2025). A fetus that does not grow beyond the 10th percentile of conventionally accepted weight for gestational age. "Indeed, increased levels of pro-inflammatory cytokines such as interleukin-8, interferon-gamma, and tumor necrosis factor-alpha have been observed in individuals born with fetal growth restriction." (PMID 34576323, 2021).
fibromyalgia (5 papers, 2024 to 2025). A chronic disorder of unknown etiology characterized by pain, stiffness, and tenderness in the muscles of neck, shoulders, back, hips, arms, and legs. "Human studies in fibromyalgia have demonstrated increased Th1 type signature of CD4+ T cell subpopulations, with associated increases in interferon-gamma (IFNγ) and TNFα production and correlation with disease severity." (PMID 40002538, 2025).
generalized anxiety disorder (5 papers, 2021 to 2025). An anxiety disorder characterized by excessive and difficult-to-control worry about a number of life situations. "In a meta-analysis of inflammatory mediators in patients with generalized anxiety disorder, a higher number of immune cells producing pro-inflammatory cytokines, such as TNF-α, IL-2, and interferon-gamma (IFN-γ), was found." (PMID 40507852, 2025).
genital herpes (5 papers, 2006 to 2025). Herpes simplex infection of the genitals, most commonly caused by the herpes simplex-2 virus. "Indeed, increased CD4+ mediated production of IFNγ has previously been reported as a consequence of using liposome-DNA complexes as an adjuvant for genital herpes vaccines and for delivery of a mycobacterial hsp65 DNA vaccine." (PMID 20637091, 2010). "As previous studies have shown that IL-18 is also dispensable for stimulating IFNγ from adaptive memory immune responses, IL-18, along with type I IFN, may present attractive targets for therapeutics aiming to reduce inflammation during genital herpes." (PMID 34047696, 2021).